ZG16 (zymogen granule protein 16)
Diseases named in the same sentence as ZG16 in open-access papers (continued):
Sharing a sentence is not in itself a finding about the gene and the disease.
tumor (continued). "Furthermore, three genes (CLCA1, UGT2A3, and ZG16) were significantly downregulated in tumor tissues." (PMID 41602387, 2026). "Furthermore, IHC experiment was carried out to show that the ZG16 protein expression was downregulated in 136 CRC tumor tissues compared with the paired adjacent-normal tissues." (PMID 39114307, 2024). "Including the recently reported role of the ZG16 protein in tumor immune regulation, CRISPR may elucidate its regulatory mechanism in tumor immunity in the future." (PMID 37020597, 2023). "Importantly, ZG16 overexpression suppressed tumor growth in two syngeneic mouse models through blockage of PD-L1 expression in cancer cells meanwhile suppression of PD1 expression in T cells." (PMID 35831911, 2022). "Specifically, ZG16 overexpression promotes the polarization of TAMs from M2 to M1 type, inhibits the proliferation, growth, invasion, and migration of Panc-1 cells, enhances immune activation within the tumor microenvironment in vivo, and also mitigates immune resistance in mouse PDAC." (PMID 39958358, 2025). "To elucidate the influence of PD-L1 disruption and ZG16 overexpression on inhibiting PDAC progression, we conducted immunohistochemical analysis and profiled tumor-infiltrating lymphocytes." (PMID 39958358, 2025). "Real-time quantitative PCR results disclosed that MPC1, ZG16, RBM47, CPM and DNASE1L3 were expressed at higher levels in adjacent normal tissues than in tumor tissues, and SMOX expression was higher in tumor tissues than in non-tumor tissues." (PMID 38914961, 2024). "The expression of TF-protein YY1 (a regulator of CXCL8, ADH1C, CEMIP, ZG16, and CLCA4) contributes to tumor growth differs in different cancers." (PMID 36991484, 2023). "Reduces tumor weight, increases the levels of IFN-γ, TNF-α, GZMB and the expression of CLCA3, TFF3, AGR2, Zg16, Pla2g10, Guca2a." (PMID 35548468, 2022). "Since the critical role of ZG16 in CRC cell growth and tumor initiation, it is important to understand the upstream regulation of ZG16 in CRC." (PMID 27880730, 2016). "Through comprehensive analysis of the TCGA dataset, we identified an interesting gene, ZG16, which is significantly decreased in CRC samples compared to adjacent non-tumor samples." (PMID 27880730, 2016). "Furthermore, both PD-L1 knockout and ZG16 overexpression in cancer cells can target PD-L1 and CTLA4 within the tumor immune microenvironment." (PMID 39958358, 2025). "When tumor lesions develop in tissues, a notable reduction or absence of ZG16 expression can be detected." (PMID 39958358, 2025). "After 42 days, immunohistochemical (IHC) staining of tumour tissues indicated that ZG16 expression was significantly increased in the pLenti-ZG16 stably transfected LGR5+ CRC tumors, while significantly decreased in p-miR-196a stably transfected LGR5- CRC tumours." (PMID 27880730, 2016).
cancer (13 papers, 2016 to 2025). A tumor composed of atypical neoplastic, often pleomorphic cells that invade other tissues. "Several cancers related markers, including ZG16, SLPI were observed in exercise saliva, associated with electrolyte permeabilities." (PMID 34185420, 2021). "ZG16 is decreased in several cancers, such as colorectal cancer or hepatocellular carcinoma, and further evidence is needed to prove electrolyte imbalance association to cancer." (PMID 34185420, 2021). "Since ZG16 is significantly upregulated in LM upon LDM topotecan treatment, ZG16 might be an interesting target for cancer therapy." (PMID 33375322, 2020). "Association with multiple clinicopathological features indicates that ZG16 may play an important role in cancer initiation and progression." (PMID 29661177, 2018). "We further investigated the potential correlation of ZG16 with cancer stem cell markers of CRC." (PMID 27880730, 2016). "However, ZG16 and ADAMTS9, which have been ascribed roles in the control of cancer development, were also down-regulated." (PMID 32366023, 2020).
adenocarcinoma (3 papers, 2018 to 2024). A common cancer characterized by the presence of malignant glandular cells. "Our data showed that sequential down-regulation of ZG16 from early precancerous lesions to adenocarcinoma was associated with the molecular phenotypes of these tumors being MSI-H and CIMP-H, and/or exhibiting MLH1 silencing." (PMID 29661177, 2018). "Through systematic evaluation by IHC, our data showed sequential down-regulation of ZG16 from partial loss of its expression in the neoplastic precursor adenomatous polyps to complete loss in the resultant adenocarcinoma, support the role of ZG16 loss as early event during CRC initiation." (PMID 29661177, 2018). "ZG16 loss is also an early event in the development of CRC, as seen in the transition from adenomatous polyps to adenocarcinoma." (PMID 39114307, 2024).
ZG16 also shares sentences with these, for which no sentence is quoted: breast carcinoma (2 papers); Chronic colitis (1); colorectal (1); coronary heart disease (1); diverticulitis (1); hepatocellular carcinoma (1); hypertriglyceridemia (1); immune dysfunction (1); infection (1); pancreatic ductal adenocarcinoma (1); pancreatitis (1); rectal cancer (1); ulcerative colitis (1).